ARHGEF11 (Rho guanine nucleotide exchange factor 11)
Diseases named in the same sentence as ARHGEF11 in open-access papers:
ARHGEF11 is named in the same sentence as 39 diseases in open-access papers, as found by Europe PMC text mining. Sharing a sentence is not in itself a finding about the gene and the disease. The quoted sentences say what the papers report.
breast carcinoma (5 papers, 2017 to 2023). "Intriguingly, a tendency for the co-occurrence of mutations in Arhgef11 and Plekha5 was observed in our single-cell data, as well as in analyzed human breast cancer data." (PMID 32978388, 2020). "Moreover, the exon 38-containing ARHGEF11 splice isoform was closely associated with the malignant phenotype of breast cancer." (PMID 33122451, 2020). "Here we analyzed the functional consequences of ARHGEF11 splice isoform expression in breast cancer cells." (PMID 29190905, 2017). "Our study provides clear evidence that the isoform expression of ARHGEF11 has particular functional relevance to the malignant phenotype of breast cancer cells, and identifies ARHGEF11 as a potential target for cancer therapy." (PMID 29190905, 2017). "Here we demonstrate that the expression of the specific splice isoform of ARHGEF11 has critical impact in breast cancer cells." (PMID 29190905, 2017). "We show here that ARHGEF11 shows splice isoform expression that differs according to the intrinsic subtype of breast cancer cells and that controls their invasive phenotype." (PMID 29190905, 2017). "Moreover, depletion of ARHGEF11 in basal breast cancer cells is sufficient to alter cell morphology, which suppresses the cancer cell growth and survival in vitro and in vivo." (PMID 33845831, 2021). "Finally, to understand the role of Arhgef11 in tumor progression, we performed CNVs screen in several breast cancer cell lines using ddPCR and found copy-number gain of Arhgef11 in 4T1 cells." (PMID 32978388, 2020). "In addition, ARHGEF11 was shown to promote breast cancer cells motility via inhibiting cell tight junctions." (PMID 33122451, 2020). "Likewise, upregulation of ARHGEF11 had been identified in gallbladder cancer, glioblastoma multiforme, breast cancer and colon cancer, and was related to tumor metastasis." (PMID 33122451, 2020). "Depletion of ARHGEF11 in basal subtype breast cancer cells is sufficient to alter cell morphology from a mesenchymal stellate form with extensive cell protrusions to a cobblestone-like epithelial form, and to suppress growth and survival both in vitro and in vivo." (PMID 29190905, 2017). "Thus, inclusion of exon 38 in ARHGEF11 confers active, protumorigenic properties in breast cancer cells." (PMID 29190905, 2017). "Previous studies show that the expression of the ARHGEF11 isoform containing exon 38 is correlated to the malignant phenotype in breast tumours, which means ARHGEF11 exon 38(+) could be used as a biomarker and target of breast cancer management." (PMID 38002944, 2023). "However, how regulation of ARHGEF11 could affect the invasive phenotype of breast cancer cells was unknown." (PMID 29190905, 2017). "Luminal subtype breast cancer cells express the isoform of ARHGEF11 lacking exon 38 (38-), which binds to ZO-1 at PJAR and is necessary for formation and maintenance of cell-cell junctions." (PMID 29190905, 2017).
schizophrenia (5 papers, 2015 to 2023). A major psychotic disorder characterized by abnormalities in the perception or expression of reality. "ARHGEF11 haplotypes such as C-C of rs6427340-rs6427339 and A-C-C of rs822585-rs6427340-rs6427339 were shown to be associated with schizophrenia (p = 0.0010 and 0.0018, respectively), but the ARHGEF11 SNPs were not." (PMID 37958606, 2023). "Recently, several variants of RhoA-associated GAPs, including ARHGAP10, ARHGAP18, and p250GAP, and GEFs such as KALRN and ARHGEF11, were reported to be significantly associated with the development of schizophrenia." (PMID 37958606, 2023). "ARHGEF11 variants are associated with a higher risk for the onset of schizophrenia in a Japanese population." (PMID 33315097, 2021). "Some variants of ARHGEF11 have been associated with type 2 diabetes and schizophrenia in several ethnic populations." (PMID 29380240, 2018). "We found that ARHGEF11 variants are associated with a higher risk for the onset of schizophrenia in a Japanese population." (PMID 28036092, 2016). "It is reported that ARHGEF11 variants are associated with schizophrenia and T2DM in multiple ethnic populations." (PMID 28036092, 2016). "There have been several other human studies that have identified an association between ARHGEF11 and metabolic, inflammatory diseases, and psychiatric disorders, such as impaired glucose tolerance and diabetes, susceptibility to intracranial aneurysm, and schizophrenia." (PMID 26172442, 2015). "On the other hand, in situ hybridization analysis indicated that ARHGEF11 mRNA levels in the thalamus of patients with schizophrenia were higher than those in healthy controls." (PMID 37958606, 2023). "The way ARHGEF11 in dendritic spines contributes to the pathogenesis of schizophrenia is unknown, thus we studied the distribution, binding, and functions of ARHGEF11 in the dendritic spine of the rat cerebral cortex." (PMID 28036092, 2016). "Alterations in ARHGEF11 gene and ARHGEF11 protein expression might contribute to the pathophysiology of schizophrenia." (PMID 28036092, 2016). "ARHGEF11 variants are reported to be associated with a higher risk for the onset of schizophrenia in a Japanese population; however, how ARHGEF11 contributes to the pathogenesis of schizophrenia in dendritic spines is unknown." (PMID 28036092, 2016). "The functions of ARHGEF11 haplotypes associated with schizophrenia have not been clarified." (PMID 37958606, 2023). "Thus, altered ARHGEF11 expression may play a role in the pathophysiology of schizophrenia." (PMID 28036092, 2016). "Although, the importance of ARHGEF11/PSD-95 interaction is not clear in this study, ARHGEF11 (schizophrenia-related gene ARHGEF11) might play a role in glutamate receptor-mediated synaptic plasticity through regulation of RhoA signaling to the actin cytoskeleton." (PMID 28036092, 2016).
leukemia (4 papers, 2013 to 2022). A malignant (clonal) hematologic disorder, involving hematopoietic stem cells and characterized by the presence of primitive or atypical myeloid or lymphoid cells in the bone marrow and the blood. "The relationship between ARHGEF11-activated Rho with leukemia, prostate cancer, and embryonic development and modulating insulin signaling was sequentially reported." (PMID 31612150, 2019).
type 2 diabetes (3 papers, 2015 to 2019). "Numerous studies have confirmed the correlation between a R1467H variant in ARHGEF11 and type 2 diabetes." (PMID 31612150, 2019). "Regulation of ARHGEF11 on IRS1 signaling and the correlation with type 2 diabetes are important for glucose and fatty acid metabolism." (PMID 31612150, 2019).
glioblastoma (2 papers, 2020 to 2023). The most malignant astrocytic tumor (WHO grade IV). "Rho guanine nucleotide exchange factor 11 (ARHGEF11) has been proved to promote tumor metastasis in glioblastoma and ovarian carcinoma." (PMID 33122451, 2020). "Overexpression of ARHGEF11 was required for TROY-induced glioblastoma tumor cell invasion and survival." (PMID 33122451, 2020). "Recent studies have demonstrated that ARHGEF11 could induce metastasis in glioblastoma and ovarian carcinoma by promoting cell invasion and migration." (PMID 33122451, 2020).
Hypertension (2 papers, 2022 to 2025). The presence of chronic increased pressure in the systemic arterial system. "In Dahl salt-sensitive rats, loss of the Rho GEF Arhgef11 attenuates ROCK activation, decreased vascular contractility, and protection against hypertension-induced renal injury." (PMID 41301525, 2025). "Increased ARHGEF11 expression in the Dahl salt-sensitive (SS) rats leads to actin cytoskeleton-mediated changes in cell morphology and cell function that promote hypertension and a decline in kidney function." (PMID 35811723, 2022). "This highlights Arhgef11 as an upstream regulator of the RhoA/ROCK pathway in hypertension." (PMID 41301525, 2025). "Moreover, in vitro experiments were not performed, and future studies applying ARHGEF11 gene knockout technology will provide a more detailed view of the molecular changes, combined with cellular level changes, in hypertension induced by activating the RhoA/ROCK signaling pathway." (PMID 35811723, 2022).
metabolic syndrome (2 papers, 2019 to 2021). A cluster of metabolic risk factors for CARDIOVASCULAR DISEASES and TYPE 2 DIABETES MELLITUS. "Here, we established that severe hyperglycemia during pregnancy could lead to obesity and increased risk of metabolism syndrome in female F2 offspring rats by affecting the expression of ARHGEF11 and insulin signaling molecules in the liver and muscles." (PMID 31612150, 2019).
Obesity (2 papers, 2015 to 2019). Accumulation of substantial excess body fat. "Several studies have confirmed that ARHGEF11 affects the metabolism of glucose and fatty acids through the insulin signaling pathway and acts as a key determinant of metabolism- and obesity-associated pathologies." (PMID 31612150, 2019). "However, the expression of ARHGEF11 and insulin signaling molecules in muscle tissues showed an opposing trend, which suggests complex regulation patterns of obesity and metabolism in the offspring of gestational hyperglycemia parents." (PMID 31612150, 2019). "The expression of ARHGEF11 was significantly higher in the livers of the F2G♀C♂ and F2G♀G♂ groups, and insulin signaling molecules were accordingly suppressed, which may explain an influential factor for obesity in F2 offspring." (PMID 31612150, 2019).
chronic kidney disease (1 paper, 2015). Impairment of the renal function secondary to chronic kidney damage persisting for three or more months. "Through positional cloning, Arhgef11, a Rho guanine nucleotide exchange factor was previously implicated in kidney injury and reduced function exhibited by the Dahl salt-sensitive (S) rat, a model of hypertensive related chronic kidney disease (CKD)." (PMID 26172442, 2015).
glomerulosclerosis (1 paper, 2015). A hardening of the kidney glomerulus caused by scarring of the blood vessels. "However, by week 24, the S rat demonstrated significant glomerulosclerosis and tubulointerstitial injury (demonstrated by blue staining), which was significantly attenuated in the Arhgef11-congenic." (PMID 26172442, 2015).
hepatoma (1 paper, 2020). "Moreover, the weakly metastatic cell lines (SNU-182, Hep3B and Huh7) expressed a lower level of ARHGEF11, suggesting that ARHGEF11 might be associated with the metastatic potential of hepatoma cells." (PMID 33122451, 2020). "ARHGEF11-silenced hepatoma cells displayed a clear increase in E-cadherin and a decrease in Vimentin as well as ZEB1 compared with the control group." (PMID 33122451, 2020). "ARHGEF11 downregulation significantly inhibited the cell viability of hepatoma cells as detected by CCK-8 assay." (PMID 33122451, 2020). "Increased G0/G1 phase and decreased S phase proportions were observed in ARHGEF11-silenced hepatoma cells." (PMID 33122451, 2020). "To further explore the ARHGEF11 roles in proliferation of hepatoma cells, we detected the cell cycle after knocking down ARHGEF11." (PMID 33122451, 2020). "Moreover, it was shown that downregulation of ARHGEF11 significantly weakened the motilities of hepatoma cells." (PMID 33122451, 2020). "Silencing ARHGEF11 of the hepatoma cells induced an epithelial phenotype." (PMID 33122451, 2020). "In additon, five hepatoma cell lines were used to detected ARHGEF11 expression levels." (PMID 33122451, 2020). "We used the β-catenin agonist LiCl (40 mM), which could completely rescue the phenotype of ARHGEF11 silence, including proliferation and migration of hepatoma cells." (PMID 33122451, 2020). "In the current study, it was shown that upregulation of ARHGEF11 could promote the proliferation, migration and invasion of hepatoma cells through induction of β-catenin nuclear translocation." (PMID 33122451, 2020). "Here, we found that ARHGEF11 was upregulated in HCC samples and highly metastatic hepatoma cell lines." (PMID 33122451, 2020). "To understand the functions of ARHGEF11 upregulation in HCC progression, we silenced ARHGEF11 expression with two siRNAs (siARHGEF11-1 and siARHGEF11-2) in two highly metastatic hepatoma cell lines: HCCLM3 and SKHEP1." (PMID 33122451, 2020). "In our study, it was shown that ARHGEF11 promoted proliferation and EMT of hepatoma cells via activating β-catenin pathway." (PMID 33122451, 2020). "However, the role of ARHGEF11 in hepatocellular carcinoma (HCC) progression is largely unknown." (PMID 33122451, 2020).
Hyperglycemia (1 paper, 2019). An increased concentration of glucose in the blood. "In this study, we established a severe intrauterine hyperglycemia rat model and tested the glycolipid metabolism of two generations of offspring and investigated the expression of ARHGEF11, PI3K, and AKT in the dominant metabolic organs: the liver and muscle." (PMID 31612150, 2019).
hypertensive chronic kidney disease (1 paper, 2015). "Previously, genetic analyses identified that variants in Arhgef11 may influence kidney injury in the Dahl salt-sensitive (S) rat, a model of hypertensive chronic kidney disease." (PMID 26172442, 2015).
invasive breast carcinoma (1 paper, 2017). A carcinoma that infiltrates the breast parenchyma. "The insertion of 32 amino acids coded by exon 38 of ARHGEF11 observed in invasive breast cancer cells abolished its interaction with ZO-1 and changed its subcellular localization from cell-cell junctions to cell edge and cytoplasm." (PMID 29190905, 2017). "While the process by which ARHGEF11exon38(+) affects cell cycle mediators is still unknown, these results clearly connect the specific splice isoform of ARHGEF11 in growth of invasive breast cancer cells." (PMID 29190905, 2017).
invasive ductal carcinoma (1 paper, 2017). "Importantly, the similar splicing changes were detected in samples from invasive ductal carcinoma patients for several genes, including ARHGEF11." (PMID 29190905, 2017).
osteoporosis (1 paper, 2026). A condition of reduced bone mass, with decreased cortical thickness and a decrease in the number and size of the trabeculae of cancellous bone (but normal chemical composition), resulting in increased fracture incidence. "Na-DHA may increase osteoporosis risk by upregulating LCMT1, downregulating ARHGEF11 and VCAM1, and disrupting lipid metabolism and the balance between osteogenesis and adipogenesis, ultimately disrupting bone metabolic homeostasis." (PMID 41804343, 2026).
renal fibrosis (1 paper, 2015). A final common manifestation of a wide variety of chronic kidney diseases characterized by glomerulosclerosis and tubulointerstitial fibrosis. "PTC derived from the S kidney were more prone to EMT, a hallmark feature of the development of renal fibrosis, compared to Arhgef11-congenic derived cells." (PMID 26172442, 2015).
uveal melanoma (1 paper, 2023). A melanoma derived from melanocytes of the uveal tract. "Expressions of GNAQ, ARHGEF11, RHOJ and the fourteen selected signaling partners, analyzed in TCGA uveal melanoma patients and uveal melanoma cell line datasets, revealed parallelism, with GNAQ, ARHGEF11, and RHOJ being among the highest expressed transcripts in both groups." (PMID 37958718, 2023).
cancer (7 papers, 2008 to 2023). A tumor composed of atypical neoplastic, often pleomorphic cells that invade other tissues. "Five of these 25 alternatively spliced genes are well-known to play a role in cancer (ARHGEF11, CD44, CTNND1, ENAH, MBNL1)." (PMID 33845831, 2021). "The other genes (SMARCE1, DISC1, CENTD2, RHOT1, ARHGAP6, ARHGEF9 and ARHGEF11) are also involved in cancer progression or chemoresistance." (PMID 23300757, 2012). "HeLa cell lysate was also used in the other western blots, with expression of ARHGEF1, ARHGEF11, ARHGEF12, ARHGAP5, ARHGAP24 and ARHGDIA protein reported in this cancer cell line." (PMID 18190708, 2008).
tumor (4 papers, 2017 to 2023). "Furthermore, univariate and multivariate analysis identified high ARHGEF11 expression, together with larger tumor size and advanced BCLC stage, as three independent risk factors for OS." (PMID 33122451, 2020). "Of note, 65% (13/20) of 153LMT cells and 44% (8/18) of 153PT cells contained both the Arhgef11 mutation and the Plekha5 mutation, highlighting the power of single-cell technology in predicting possible collaborative actions for tumor evolution and tumor metastasis." (PMID 32978388, 2020). "A prognostic nomogram model that integrated ARHGEF11, tumor size and BCLC classification showed good performance in predicting clinical outcomes of HCC patients." (PMID 33122451, 2020). "Furthermore, public HCC datasets were used to compare ARHGEF11 expressions between tumor and normal tissues." (PMID 33122451, 2020). "The results showed much smaller tumor volume observed in Arhgef11-KO groups than the control group, suggesting copy-number gain of Arhgef11 is a tumor driving event and Arhgef11 plays an oncogene role in tumor progression." (PMID 32978388, 2020). "Then, we knocked out Arhgef11 in 4T1 cells using the CRISPR/Cas9 system with two different sgRNAs and implanted the knockout cells into the mammary fat pads of BALB/c mice to monitor tumor growth." (PMID 32978388, 2020).
ARHGEF11 also shares sentences with these, for which no sentence is quoted: breast tumors (2 papers); gallbladder cancer (2); ovarian carcinoma (2); prostate carcinoma (2); colon cancer (1); diabetes (1); Glucose intolerance (1); Impaired glucose tolerance (1); infection (1); Insulin resistance (1); intracranial aneurysm (1); kidney injury (1); lung carcinoma (1); macrosomia (1); melanoma (1); metastatic tumors (1); non-alcoholic fatty liver (1); placental insufficiency (1); psychiatric disorder (1).